ATRAID (all-trans retinoic acid induced differentiation factor)
Description:
Promotes osteoblast cell differentiation and terminal mineralization. Plays a role in inducing the cell cycle arrest via inhibiting CCND1 expression in all-trans-retinoic acid (ATRA) signal pathway. In osteoclasts, forms a transporter complex with ATRAID for nitrogen-containing-bisphophonates (N-BPs) required for releasing N-BP molecules that have trafficked to lysosomes through fluid-phase endocytosis into the cytosol.
Synonyms: APR-3; APR3; C2orf28; HSPC013; p18; APR--3; PRO240
Tractability: Antibody: UniProt places it where antibodies can reach, with high confidence; UniProt predicts a signal peptide or a membrane-spanning region; its Gene Ontology location is reachable by antibodies, with medium confidence. PROTAC: ubiquitination databases record sites on it.
Gene: Protein-coding gene on chromosome 2 (27,212,041 to 27,217,178, forward strand). Ensembl gene ENSG00000138085.
Subcellular location: Nucleus envelope; Cell membrane; Lysosome membrane
Gene Ontology:
Molecular function: protein binding; xenobiotic transmembrane transporter activity
Biological process: negative regulation of osteoblast proliferation; negative regulation of protein catabolic process; positive regulation of bone mineralization; positive regulation of osteoblast differentiation; regulation of gene expression; xenobiotic transmembrane transport
Cellular component: lysosomal membrane; nuclear envelope; perinuclear region of cytoplasm; plasma membrane
Genetic constraint (gnomAD): Loss-of-function variants: 26 observed, 29.2 expected, observed/expected ratio (o/e) 0.89, 90% interval 0.65 to 1.24. The upper end of that interval is the gene's LOEUF score, 1.24, which puts it in group 5 of 6, group 1 being the genes least tolerant of losing a copy. Missense variants: 308 observed, 289.23 expected, observed/expected ratio (o/e) 1.06, 90% interval 0.97 to 1.17. Synonymous variants: 131 observed, 110.01 expected, observed/expected ratio (o/e) 1.19, 90% interval 1.03 to 1.38.
Homologues: Orthologues: chimpanzee ATRAID (98% identical), macaque ATRAID (95% identical), dog ATRAID (81% identical), rabbit ATRAID (77% identical), rat Atraid (70% identical), mouse Atraid (62% identical), pig ATRAID (57% identical), tropical clawed frog atraid (42% identical), guinea pig Atraid (41% identical), zebrafish atraid (38% identical).
Diseases named in the same sentence as ATRAID in open-access papers:
ATRAID is named in the same sentence as 5 diseases in open-access papers, as found by Europe PMC text mining. Sharing a sentence is not in itself a finding about the gene and the disease. The quoted sentences say what the papers report.
osteoporosis (1 paper, 2025). A condition of reduced bone mass, with decreased cortical thickness and a decrease in the number and size of the trabeculae of cancellous bone (but normal chemical composition), resulting in increased fracture incidence. "ATRAID (all-trans retinoic acid-induced differentiation factor), is a genetic target of nitrogen-containing-bisphosphonates (N-BP), a commonly used drug to treat osteoporosis and other bone-related diseases." (PMID 40186177, 2025).
ATRAID also shares sentences with these, for which no sentence is quoted: bone disorder (1 paper); cancer (1); nephropathies (1); nephrotic syndrome (1).